CRP (C-reactive protein)
Diseases named in the same sentence as CRP in open-access papers (continued):
Sharing a sentence is not in itself a finding about the gene and the disease.
metabolic syndrome (continued). "Obese with metabolic syndrome group had higher CRP and insulin level in comparison with obese without metabolic syndrome group." (PMID 22691465, 2012). "CRP levels increased significantly in the group of obese children with or without metabolic syndrome compared to control group." (PMID 22691465, 2012). "We evaluated the use of hs-CRP to discriminate between centrally obese people with and without the metabolic syndrome." (PMID 22417460, 2012). "The body weight, BMI, waist circumference, systolic and diastolic blood pressure, as well as TC, LDL-C, TG, leptin, and CRP levels were significantly higher in the obese group without metabolic syndrome than in the control group." (PMID 22691465, 2012). "The aim here was to evaluate cardiovascular risk through the Framingham Risk Score (FRS) criteria, C-reactive protein (CRP) assays and presence of metabolic syndrome (MS) in men with and without erectile dysfunction diagnosed within a healthcare program." (PMID 20963365, 2010). "The mean waist circumference (P = 0.001), BMI (P = 0.00), systolic blood pressure (P = 0.001), diastolic blood pressure (P = 0.001), hs-CRP (P = 0.006) and IMT of left carotid artery (P = 0.02) were significantly higher in participants with metabolic syndrome (case group)." (PMID 22577415, 2010). "We have previously reported in the serum, liver and adipose tissue of morbidly obese patients that elevated CRP expression levels were independent of metabolic syndrome, type 2 diabetes and NASH." (PMID 21042596, 2010). "Recent studies have shown that high levels of C-reactive protein (C-RP), an indicator of systemic inflammation, are associated with increased risk of AMI (as well as metabolic syndrome and type 2 diabetes), independent of the level of CAS." (PMID 16451853, 2006). "In this context, Rinaldi et al13 recently developed a risk-scoring system, the ABCD score, consisting of MINOCA presentation, myocardial bridge (MB), C-reactive protein (CRP), and dyslipidemia, to predict positive ACh test results, which has not been externally validated yet." (PMID 40373526, 2025). "HbA1c (OR:1.42, CI:1.19-1.70, and OR:1.31, CI:1.12-1.54) and serum Cr (OR:2.93, CI:1.06-8.09, and OR:2.50, CI:1.06-5.88) were significant predictors of both HTN and non-HTN classes respectively, while serum vitamin D and CRP level were no significant predictors of metabolic syndrome classes." (PMID 40093747, 2025). "Notably, serum CRP and vitamin D levels did not emerge as significant predictors of metabolic syndrome latent classes, except for serum CRP in the HTN class among women." (PMID 40093747, 2025). "Diets high in saturated fats and sugars have been shown to lead to dyslipidemia by increasing TG and decreasing HDL-C levels, thereby promoting an atherogenic lipid profile, which is often accompanied by elevated inflammatory markers such as C-reactive protein (CRP) and interleukin-6 (IL-6)." (PMID 40077646, 2025). "Finally, in patients with metabolic syndrome who consumed black raspberry for 12 saw significant decreases in total serum cholesterol levels and inflammatory cytokines, including IL-6, TNF-α, CRP, sICAM-1, and sVCAM-1, ultimately improving vascular endothelial function." (PMID 41156509, 2025). "Furthermore, the study did not control for conditions that influence CRP or cortisol synthesis, such as dyslipidemia, statin therapy, or autoimmune diseases." (PMID 40566547, 2025). "Inflammatory mediators such as C-reactive protein (CRP), interleukin-6 (IL-6), and tumor necrosis factor-alpha (TNF-α) are elevated in both periodontitis and metabolic syndrome, suggesting a bidirectional relationship where each condition may exacerbate the other." (PMID 39338063, 2024). "Likewise, when considering women without metabolic syndrome, only equol-producers had significant reductions in diastolic BP (p = 0.02) and CRP (p = 0.04)." (PMID 38399451, 2024).
metabolic syndrome (continued). "The objective of this work is to review whether patients with OLP show higher dyslipidemia and CRP levels compared to a healthy control population without OLP." (PMID 39200771, 2024). "For this reason, the objective of this systematic review is focused on how to answer the PICO question of whether patients with OLP show higher dyslipidemia and CRP levels compared to a healthy control population without OLP." (PMID 39200771, 2024). "Furthermore, further data regarding metabolic syndrome, such as blood pressure, insulinemia, C-reactive protein, and uric acid, were not obtainable, though key cardio-metabolic markers were included in the analysis." (PMID 37360304, 2023). "Moreover, a recent clinical trial showed that periodontal treatment improved periodontal parameters in metabolic syndrome patients, but no improvement was found in metabolic parameters such as HbA1c, waist circumference, CRP levels, and more." (PMID 37629193, 2023). "Importantly, such effects were consistent with effective modulation of the prominent markers of dyslipidemia, inflammation, and oxidative stress, including low-density lipoprotein (LDL)-cholesterol, and high sensitivity C-reactive protein (hs-CRP) and plasma GSH levels." (PMID 36839303, 2023). "In a study from Iran, hs-CRP ≥ 3 mg/L was not a significant predictor of CVD among people with dyslipidemia whereas, in another study, hs-CRP > 3 mg/L contributed significantly to an increased odds of CVD in subjects with HDL-C < 60 mg/dL than subjects with HDL-C ≥ 60 mg/dL." (PMID 37403063, 2023). "Dyslipidemia was not an independent factor associated with ANGPTL4, CRP, and ESR." (PMID 36790644, 2023). "Patients with severe OSA more frequently had metabolic syndrome and significantly higher levels of glucose, creatinine, uric acid, AST, ALT, CK, microalbumine/creatinine ratio, triglyceride, total cholesterol, HDL, total cholеsterol to HDL‐C ratio, CRP, and ESR." (PMID 35694268, 2022). "And it was also indicated that SUA might take part in stimulating the secretion of inflammatory markers such as C-reactive protein (CRP), interleukin (IL)-6, IL-18, and tumor necrosis factor (TNF)-alpha which are crucial to the development of metabolic syndrome." (PMID 35673358, 2022). "The influencing of aging and dyslipidemia involved in progressing inflammatory and degenerative process, on serum hs-CRP level could not ruled out." (PMID 37654837, 2022). "In patients with acute ischemic stroke and metabolic syndrome, measures of arterial stiffness (carotid–femoral PWV and aortic augmentation index) and inflammatory cytokines (TNF-α and IL-6), along with CRP, were increased compared to patients with acute ischemic stroke without metabolic syndrome." (PMID 34202323, 2021). "CRP is currently an extensively utilized biomarker for monitoring inflammation in the paediatric and neonatal populations, and children with metabolic syndrome have shown to be approximately three times more likely to have an elevated CRP level than those without metabolic syndrome." (PMID 32967204, 2020). "Moreover, the presently available methods for the detection and quantification of metabolic syndrome (MS) specific markers (C-reactive protein) by modified screen-printed electrodes has not been summarized in any other paper." (PMID 32722552, 2020). "Thus, in patients with metabolic syndrome, vitamin D therapy resulted in significant IL-6 reduction but did not change CRP concentration." (PMID 32825324, 2020). "As an example, in healthy adults, the consumption of PS-enriched soy milk reduced lipid peroxidation and inflammatory markers, whereas in individuals with metabolic syndrome the PS treatment did not affect inflammatory biomarkers such as CRP, VCAM, ICAM, IL-6, CD40 ligand, E-selectin, and MCP-1." (PMID 32455866, 2020).
metabolic syndrome (continued). "Currently, HNF1A gene variants are associated with maturity onset diabetes of the young (MODY), C-reactive protein (CRP) levels, gamma-glutamyl transferase (GGT) levels, total cholesterol (TC) levels, pancreatic cancer, coronary artery disease, and metabolic syndrome (MS)." (PMID 31915469, 2019). "In our study, seven participants were diagnosed with themetabolic syndrome and of the thirteen individuals without classical metabolic syndrome,most had some metabolic abnormalities: five had elevated plasma CRP, nine were insulinresistant, and ten had abdominal adiposity." (PMID 27313852, 2016). "In humans, levels of inflammatory markers increased significantly with age in subjects without the metabolic syndrome, (P=0.009 and P=0.037 for C-reactive protein, P<0.001 and P=0.001 for fibrinogen, P<0.001 and P=0.005 for serum amyloid-A, for Caucasians and African Americans, respectively)." (PMID 25815855, 2015). "However, we are not aware of studies on the relations of CRP, the metabolic syndrome, and carotid IMT with shoulder pain and rotator cuff tendinitis." (PMID 20646281, 2010). "The metabolic syndrome (MetSyn) is characterized by a cluster of metabolic risk factors including abdominal obesity, DM or insulin resistance, non-white ethnicity, dyslipidemia, chronic hypertension and elevated inflammatory highly sensitive serum C-reactive protein (hsCRP)." (PMID 17880716, 2007). "This inflammatory process can be gauged by blood levels of C-reactive protein and, as our results showed, Cissus formulation significantly reduced the circulating concentrations of CRP thereby inhibiting the inflammatory process and possibly reducing individual components of metabolic syndrome." (PMID 16948861, 2006). "Moreover, CRP levels correlate with other components of the metabolic syndrome that are not easily measured in clinical practice, including fasting insulin, microalbuminuria, and impaired fibrinolysis." (PMID 17140429, 2006). "A previous study conducted in the general Chinese population found that the association between SF and lipid parameters persisted after adjusting for CRP levels, suggesting that low-grade inflammation may not be the sole explanation for the link between SF levels and dyslipidemia." (PMID 40151449, 2025). "In the stratified model by dyslipidemia status, increased hs-CRP was significantly related to a higher risk of stroke [HR (95%CI): 1.34 (1.03–1.74), P = 0.030], and CVD [HR (95%CI): 1.42 (1.14–1.79), P = 0.002] among subjects with normal lipid levels, not among subjects with dyslipidemia (P > 0.05)." (PMID 37403063, 2023). "Retrospective cohorts of women in the postpartum show that those with previous GDM who are obese or have features of the metabolic syndrome (MetS), have higher CRP levels compared to those without previous GDM." (PMID 37891561, 2023). "Furthermore, BMI alone may not be the main driver of increased CRP as it may be a marker for other factors driving the metabolic syndrome." (PMID 35243104, 2022). "Furthermore, metabolic syndrome, systolic blood pressure, CRP, and glycemia were statistically different between the lowest and the intermediate tertiles, while metabolic syndrome and non-HDL cholesterol were different between the intermediate and the highest ones." (PMID 34211785, 2021). "Epidemiological studies have demonstrated an increase in plasma levels of inflammatory markers such as C-reactive protein (CRP), interleukin-6 (IL-6) and tumour necrosis factor-α (TNF-α) in patients with metabolic syndrome (MetS) and also in those with clinically overt Type 2 DM." (PMID 25276234, 2014). "Although CRP and HMW-adiponectin were both significantly correlated with development of metabolic syndrome, multivariate logistic regression analysis revealed that HMW-adiponectin but not CRP was associated with metabolic syndrome independently of BMI or waist circumference." (PMID 24069195, 2013).
metabolic syndrome (continued). "This research examined the relationship between C-reactive protein (CRP) levels and lymphocyte counts in individuals with chronic obstructive pulmonary disease (COPD) comparing those with metabolic syndrome (MetS) to those without." (PMID 39347252, 2024). "In contrast, the study conducted by Inge Boers, investigating the Paleo diet, showed no significant impact on hs-CRP and TNF-a levels in individuals with metabolic syndrome during a 2-week intervention period." (PMID 38476230, 2024). "Moreover, lower SPISE index significantly correlated in adults or adolescents with the presence of T2D, metabolic syndrome, risk of cardiovascular diseases, non-alcoholic fatty liver disease (NAFLD), abdominal obesity, higher levels of C-reactive protein (CRP) and lower levels of adiponectin." (PMID 34142364, 2022). "We selected four markers: CRP, sCD200R1, CD5L, and sTLR2; in particular, sCDR2001 has not yet been measured in the context of psoriasis and metabolic syndrome." (PMID 36556186, 2022). "Patients with metabolic syndrome had significantly higher values of uric acid, gama GT, microalbumine/creatinine ratio, CRP, and ESR than patients without metabolic syndrome (p < 0.05)." (PMID 35694268, 2022). "The present meta-analysis revealed that flaxseed consumption had an overall beneficial effect on serum TC, LDL-C, TG, apo B and IL-6 in patients with dyslipidemia related diseases, but not on apo A, HDL-C, hs-CRP, CRP and anthropometric indices." (PMID 34635132, 2021). "Neutrophil-to-lymphocyte ratio was not a better indicator of inflammation compared with CRP in obese subjects with metabolic syndrome, although both CRP and NLR were simple and effective predictors of inflammation in subjects with metabolic syndrome." (PMID 30454030, 2018). "In treated patients the dyslipidemia correlates better with C-reactive protein and IL-6 levels, rather than with CD4 count or HIV viral load, suggesting that immune activation has a central role in the development of dyslipidemia." (PMID 30233499, 2018). "In subjects with CEI subtype and metabolic syndrome, PWV was more significantly and positively related to vWF but not with TNF-α, CRP, IL-6, IL-1β and PAI-1 compared to subjects without metabolic syndrome and the same subtype of stroke." (PMID 24571954, 2014). "In subjects with stroke classified as LAAS and metabolic syndrome, PWV was more significantly and positively related to CRP, IL-1β, IL-6, TNF-α, vWF and PAI-1 compared to subjects without metabolic syndrome and the same subtype of stroke." (PMID 24571954, 2014). "Although the term photoreceptor outer segment has no biological relevance to CRP or inflammation, the genes enriched in this pathway have biological relevance to CRP (HNF1A), high triglycerides (PCDH15) and metabolic syndrome (GNAT3)." (PMID 24763700, 2014). "The present study shows that Z-scores of CRP, SAA, sICAM-1, sVCAM-1 differed across categories of glucose metabolism, weight, metabolic syndrome and smoking status in a similar fashion irrespective of the method of detection." (PMID 23472208, 2013). "As a result, ROC analysis revealed that adding CRP and HMW-adiponectin to the traditional markers did not improve the predictive ability for metabolic syndrome." (PMID 24069195, 2013). "CRP and C/A ratio were significantly higher, and HMW-adiponectin was significantly lower in subjects who developed metabolic syndrome compared with those who did not (all p<0.001)." (PMID 24069195, 2013). "In conclusion, in this study we reported that CRP, HMW-adiponectin or the combination of both did not improve the predictive value of BMI and waist circumference for metabolic syndrome." (PMID 24069195, 2013). "The obese participants without metabolic syndrome presented significant reductions in weight, BMI, TC, LDL-C, CRP and leptin, and an increase in HDL-C in response to training." (PMID 22691465, 2012).
metabolic syndrome (continued). "In a separate study, the inflammatory marker C-reactive protein (CRP), but not IR, was inversely related to blood plasma phospholipid and cholesteryl ester levels of ALA, as well as EPA and DHA in persons with metabolic syndrome." (PMID 19664246, 2009). "Exploratory associations with CRP and lipids showed that CHI3L1 expression did not correlate with CRP or lipid markers in healthy controls or MCI (all p > 0.05), arguing against baseline systemic inflammation or dyslipidemia as primary drivers of group differences." (PMID 41425914, 2025). "By subdividing patients in tertiles based on the concentration of 25(OH)D, subjects of the lowest and highest tertiles showed significant differences in BMI, metabolic syndrome, systolic blood pressure, LDL cholesterol, non-HDL cholesterol, glycemia, CRP, C3, and cQT." (PMID 34211785, 2021). "Thus, sarcopenic patients had higher amounts of total body fat mass (FM), more components of metabolic syndrome (MetS), HOMA-IR index, and higher C-reactive protein (CPR) levels, compared to those without sarcopenia." (PMID 35111794, 2021). "The JUPITER trial concluded that individuals with increased levels of the inflammatory biomarker C-reactive protein (CRP) responded to rosuvastatin pharmacotherapy and had significant decreases in major cardiovascular events, regardless of presence of dyslipidemia." (PMID 34760952, 2021). "In addition, our study determined that the CRP level were significantly higher in postmenopausal women with MetS than those without MetS and higher CRP level is independent factor for the presence of metabolic syndrome, which is consistent with one recent study." (PMID 23819808, 2013). "As we focused to the development of metabolic syndrome in this study, we were not able to exclude the possibility that CRP and HMW-adiponectin may be useful to predict each component of metabolic syndrome such as impaired glucose tolerance and dyslipidemia." (PMID 24069195, 2013). "Moreover, inflammatory markers including CRP and NLR could be influenced by some confounding factors that we currently lack information on, such as allergy, infection, metabolic syndrome and the use of non-steroidal anti-inflammatory drugs, within this subset." (PMID 29570259, 2019). "We determined relationships of high sensitive C-reactive protein (hs-CRP) and SAA with bilirubin in subjects with and without metabolic syndrome (MetS)." (PMID 24209691, 2013).